HMGB1 (high mobility group box 1)
Diseases named in the same sentence as HMGB1 in open-access papers (continued):
Sharing a sentence is not in itself a finding about the gene and the disease.
tumor (continued). "Activated macrophages, natural killer cells, and mature DCs can release HMGB1, which may promote a positive feedback loop to propagate subclinical inflammation, tumor initiation and progression." (PMID 33013860, 2020). "The ICD-related multiple cell death pathways of tumor cells lead to exhibit damage-associated molecular patterns (DAMPs), including calreticulin (CRT) translocation, adenosine triphosphate (ATP) secretion, and high mobility group box 1 (HMGB1) release." (PMID 33260446, 2020). "HMGB1 has been described as an alarmin or damage-associated molecular pattern (DAMP) molecule as for the central role of HMGB1 in inflammation and a relevant molecule in immune responses against tumor formation." (PMID 32708917, 2020). "In addition to HMGB1, tumor cells, including BC cells, have been reported to secrete other peptides, such as a2 isoform V-ATPase (a2V), to activate the NF-κB pathway in neutrophils, thereby promoting their recruitment and inhibiting their apoptosis." (PMID 32849640, 2020). "Interestingly, HMGB1 also has a cytokine function that has an extranuclear role when it is inactively released from necrotic and tumor cells after radiotherapy and chemotherapy or actively from monocytes and macrophages into the extracellular environment." (PMID 33117687, 2020). "Moreover, the overexpression of miR-34c, a tumor suppressor, significantly increased the levels of eIF2α and IRE1α by directly targeting the 3ʹUTR of HMGB1 and inhibits HMGB1 translation, promoting non-small cell lung cancer (NSCLC) apoptosis." (PMID 33267910, 2020). "In most cases of carcinomas, significantly increased levels of HMGB-domain proteins are observed directly within the cancer tissue, as well as a significant increase in proliferation and, accordingly, tumor growth are observed, revealing anti-apoptotic pro-oncogenic function of HmgB1." (PMID 33114717, 2020). "However, as an enhancer of senescence, HMGB1 induces tumor cells to undergo an apoptosis-to-senescence shift to improve chemotherapy effectiveness." (PMID 32660524, 2020). "HMGB1 is a critical immunosuppressive molecule in tumor microenvironment." (PMID 32477934, 2020). "Emodin dramatically reduced HMGB1 induced VEGF production leading to a reduced tumor growth." (PMID 31983185, 2020). "HMGB1 might recruit inflammatory cells or fibrotic cells to the tumor region, promoting a permissive microenvironment." (PMID 32382012, 2020). "The prominent mEHT-related upregulation and cell membrane accumulation of calreticulin after 12 h and Hsp70 after 48 h, accompanied by the nuclear-to-cytoplasmic Hmgb1 translocation and release from tumor cells from 48 h post-treatment, confirmed significant DAMP signaling." (PMID 32872532, 2020). "In contrast, HMGB1 also plays an adverse role in tumor immunity." (PMID 33013860, 2020). "Changes of HMGB1, liver function, tumor markers and immune cells after TACE." (PMID 33473353, 2020). "Lately, GA was shown to exhibit substantial toxicity in tumours of the central nerve system, suggesting that the targeting of HMGB1 with GA may be used for regulating the growth as well as development of cancers." (PMID 32902129, 2020). "However HMGB1 is a pleiotropic molecule that shows pro-tumor and tumor-restricting actions in a context specific manner." (PMID 32133298, 2020). "Preliminary results have demonstrated that apoptosis induction by HHP was accompanied by exposure/release of several immunogenic molecules, such as HSP90, HSP70, CRT, ATP, and HMGB1, in human prostate, leukemia, and ovarian tumor cell lines and/or primary tumor cells." (PMID 32178288, 2020). "However, the primary source of HMGB1 in tumor tissue culture supernatant (TTCS) was tumor cells rather than immune cells." (PMID 32943604, 2020).
tumor (continued). "Some chemotherapeutic drugs, such as doxorubicin, not only kill tumor cells and thus release tumor antigens but also elicit the appearance of a set of danger signals including ATP, HMGB1 or calreticulin, which are released into the extracellular space or exposed at the surface of dying cells." (PMID 31990272, 2020). "The dying tumor cells can release HMGB1 that matured DCs through TLR-4-dependent manner." (PMID 33643911, 2020). "HMGB1 has been reported to downregulate apoptosis in tumor cells by binding to RAGE." (PMID 32708917, 2020). "Immunoblotting showed the upregulation of HMGB1 in HCC tumor samples of the patients." (PMID 32328193, 2020). "Subsequently, qRT-PCR analysis revealed that sh-NNT-AS1 transfection decreased NNT-AS1 expression in vivo, besides that, the expression of miR-186 was increased, while HMGB1 mRNA or protein expression was reduced in tumor tissues derived from sh-NNT-AS1-transfected CC cells." (PMID 32489326, 2020). "With the higher intake of nano-LSW, the expression of PCNA, HMGB1 and other related tumor proliferation and migration factors in cells may be altered." (PMID 32754037, 2020). "Tumor cells undergoing ICD secrete distress signals through molecules called damage-associated molecular patterns (DAMPs), including calreticulin (CRT), adenosine triphosphate (ATP) and high-mobility group box 1 (HMGB1), to activate the immune response." (PMID 32317755, 2020). "Immunostaining analysis for PCNA showed a lower number of proliferating hepatocytes in the tumor and non-tumor regions of Atg7/Hmgb1ΔHep livers than those in the Atg7ΔHep livers, suggesting that HMGB1 contributed to an overall enhanced proliferation status in autophagy-deficient livers." (PMID 32382012, 2020). "Notwithstanding the various protumorigenic mechanisms involving extracellular HMGB1, this protein may also drive tumor progression when present in the tumor cell cytosol during conditions of hypoxia that prevail in the TME." (PMID 32664328, 2020). "The study demonstrates that HMGB1 secretion induced by autophagy in the tumor microenvironment during tumorigenesis can alter the plasma levels of glutamine, which is utilized as an energy source by cancer cells, and decrease pyruvate kinase isozymes M1 (PKM1)." (PMID 33604297, 2020). "However, with tumor progression, high HMGB1 expression was observed to promote tumor growth in both the 4T1 and EMT6 tumors, and lung metastasis was obvious in the 4T1-Control and EMT6-HMGB1 groups but not the 4T1-shHMGB1 and EMT6-Control groups at 4 weeks." (PMID 32943604, 2020). "One of the DAMPs that can stimulate TLR2 activation in the tumor milieu is HMGB1." (PMID 33321934, 2020). "With respect to activation of RAGE, also expressed on various cell types, including inflammatory cells and tumor cells, earlier studies identified fully reduced HMGB1 as the most prominent ligand of the two HMGB1 isoforms for this ubiquitous pro-inflammatory/pro-oxidative receptor." (PMID 32664328, 2020). "Since the effect of HMGB1 in promoting tumor development may be at least in part mediated by an altered microenvironment, there could be multiple alterations in tumor behaviors affected by this process." (PMID 32382012, 2020). "For example, Newcastle disease virus (NDV) immunotherapy has been demonstrated to promote the translocation of CRT to the cell surface and extracellular accumulation of HMGB1 in orthotopic murine glioma models, along with tumor-specific immune response and durable tumor control." (PMID 33172438, 2020). "In a separate study, HMGB1 expression level also correlated inversely with tumor differentiation." (PMID 32664328, 2020). "In addition, activation of TLR2 by endogenous extracellular matrix-derived proteoglycan versican and TLR4 by HMGB-1 from damaged cells are known to promote tumor growth in a context-dependent manner." (PMID 32422978, 2020).
tumor (continued). "Also, the effect was stronger at a low dose than at a high dose, indicating that low-dose gemcitabine treatment can induce stronger CRT and HMGB1 exposure in tumor cells." (PMID 32161598, 2020). "Intralesional therapies, such as T-VEC, BCG, PV-10, and IL2 can promote neoantigen exposure (through viral antigens, HMB-PP, HMGB1 proteins, and melan-A, respectively), possibly turning weakly immunogenic tumors into strongly immunogenic tumors and promoting anti-tumor immunity." (PMID 32455916, 2020). "In addition, the release of HMGB1 from dying tumor cells promotes interactions of toll-like receptor 4 (TLR-4), a pattern recognition receptor that signals through the TLR-4-MyD88 axis on DCs, that elicit potent immunostimulatory effects." (PMID 32317755, 2020). "Given the established role of HMGB1 and HMGB1-induced inflammation in the pathology of malignant disease, and the unique interface between immunity and tumor cells within the microenvironment established within MPEs, we examined the potential influence of HMGB1 on immune composition of MPEs." (PMID 33013860, 2020). "Dying tumour cells generated HMGB1 through PEG-TECM-NS/OLE-induced ICD." (PMID 33009382, 2020). "Both immune cells and tumor cells in primary tumors expressed high levels of HMGB1." (PMID 32943604, 2020). "Recently, HMGB1 has been shown to be expressed on tumor-derived exosomal membranes." (PMID 32551121, 2020). "HMGB1 (high mobility group box 1) is situated in the nucleus to maintain nuclear homeostasis, which plays an indispensable role in many diseases and cellular processes, like tumor, inflammation, cell differentiation, and migration." (PMID 32489453, 2020). "In addition, CRT exposure, secretion of ATP, HSP70, and HSP90, and HMGB1 release and autophagy were among the hallmarks of apoptosis induced by TcdB in intoxicated tumor cells." (PMID 32340275, 2020). "The overexpression of fibulin-3 and HMGB1 could be used to differentiate between tumor and adjacent tissues." (PMID 33230247, 2020). "For example, the ratio between GAL-9 and HMGB1 in the tumor microenvironment plays an important role in determining whether TIM-3 expression on DCs can be beneficial or detrimental to the tumor." (PMID 33425759, 2020). "Eliglustat challenge resulted in increased tumor staining positivity for HMGB1 and LC3B, consistent with induction of lethal mitophagy; although we do not rule out this may also be reflective of macroautophagy." (PMID 32855410, 2020). "Under HMGB1 stimulation, angiogenesis and immune inhibition promote tumor metastasis." (PMID 33015161, 2020). "HMGB1 mainly accumulated in the hepatocytes in the tumor area." (PMID 32754037, 2020). "In the setting of established cancers, the production of HMGB1 by tumor cells per se may also exacerbate inflammation-related immunosuppression." (PMID 32664328, 2020). "We found overexpression of fibulin-3 and HMGB1 in tumor tissue compared with adjacent tissue." (PMID 33230247, 2020). "However, as shown, eMIP can be trapped by HSP70 and HMGB1 in the tumor bed and exert their effects there." (PMID 31058025, 2019). "Furthermore, HMGB1-mediated production of thymic stromal lymphopoietin (TSLP) by tumor cells can modulate DCs via the TSLP receptor under physiological conditions." (PMID 31307548, 2019). "Moreover, the levels of anti-heat shock protein (Hsp) and anti-high mobility group box-1 (HMGB1) antibodies in cancer patients have been useful in tumor diagnosis." (PMID 30755156, 2019). "The results showed that blockade of HMGB1 signaling diminished the antitumor effect of β-lap, indicating that β-lap may induce HMGB1 release in the tumor microenvironment to enhance innate response via a TLR4/MyD88 pathway." (PMID 31324798, 2019). "Moreover, it has been demonstrated that HMGB1 released during tumor cell necrosis induces not only DC maturation, but also secretion of IL-12 by DCs and IFN-γ by T cells acting as a potent stimulus for polarization of Th1 response." (PMID 31649875, 2019).
tumor (continued). "Cisplatin and irradiation can directly kill growing tumor cells, thus more tumor antigen and danger-associated molecular patterns (DAMPs), including tumor cell DNAs, ATP, and HMGB1, would be released from dying tumor cells in the therapy-applied Oasl1−/− lungs." (PMID 31049360, 2019). "The HSP70/eMIP and HMGB1/eMIP complexes enhance anti-tumor immunity." (PMID 31058025, 2019). "The association between HMGB1 and autophagy in radiation resistance was further supported in ESCC patients as expression of LC3 positively correlated with HMGB1 in tumor tissues and patients with in-field recurrence after PORT exhibited higher LC3 expression compared with those without recurrence." (PMID 31683722, 2019). "Deletion of Hmgb1 inhibited tumor development in the DEN-induced HCC model." (PMID 31731454, 2019). "It is conceivable that platelets may serve as an intermediary between tumor cells to influence neutrophils and promote NETosis via the release of platelet-activating soluble factors, such as HMGB1." (PMID 31852512, 2019). "In fact, HMGB1 can exert both pro- and anti-tumor responses." (PMID 31779212, 2019). "Several of the RAGE ligands, including HMGB1 and some of the S100 proteins, have been linked to tumorigenesis in in vitro studies, supporting the direct mediation of RAGE in the proliferation, migration, survival, and invasion of different tumor cells." (PMID 31779212, 2019). "In addition, tumor cell-derived HMGB1 was secreted in the cell culture supernatants to a significantly higher extent compared to PBS controls." (PMID 30679720, 2019). "Furthermore, a nude murine model with transplanted tumor was employed for examining the effect of HMGB1-mediated autophagy on imaging and biodistribution of 99mTcO4−." (PMID 31331356, 2019). "The level of tumor HMGB1 expression in recurrence male patients was increased (P < 0.0001)." (PMID 30755598, 2019). "HMGB1, released from the treated tumor cells by DOC, was also inhibited by GSH." (PMID 30744691, 2019). "However, the role of extracellular HMGB1 in cancer is complex since it can be actively or passively released from immune and tumor cells and bind to different receptors." (PMID 31779212, 2019). "Interestingly, HMGB1 is involved in resistance toward tumor vessel-targeted, monoclonal antibody-based immunotherapy." (PMID 30692642, 2019). "Interestingly, autophagy-mediated intracellular mobilization of HMGB1 enables tumor growth by inducing cell survival and apoptosis." (PMID 30695997, 2019). "Individual PRRs activated by HMGB1, such as TLRs, also contribute to tumor progression." (PMID 31379812, 2019). "Since EMT has been widely regarded as a crucial process in tumor invasion and metastasis 21, we hypothesized that HMGB1 affected PCa cell migration and invasion through regulating the EMT progression." (PMID 31410208, 2019). "We infer that multiple types of ligands released by tumor cells following chemotherapy (e.g., tumor DNA, HMGB1, tumor RNA) may act through their respective TLRs to drive DC maturation and activation of tumor-specific CTLs." (PMID 31619293, 2019). "In addition, HMGB1, together with ATP, which is liberated following tumor cell insult, will drive the secretion of IL-1β from DC, thereby enhancing CD8 T cell activation." (PMID 31191545, 2019). "Tumor-derived HMGB1 triggers a CD8+ T cell antiglioblastoma response and induces TLR2 signaling." (PMID 31240216, 2019). "Additionally, the upregulation of HMGB1 in NSCLC can reduce the sensitivity of tumor cells to chemotherapy regents." (PMID 31307548, 2019). "The HMGB1-dependent tumor-specific T cell response and HMGB1-dependent antitumor effect of β-lap in vivo suggested that β-lap could potentially induce ICD in the tumor." (PMID 31324798, 2019). "Thus, HMGB1 affects anti-tumor immune responses, but further investigations are necessary to better understand the role of HMGB1 in anti-tumor immunity." (PMID 31399104, 2019).
tumor (continued). "Recently, HMGB1 was found to be passively released from irradiated tumor cells." (PMID 31015520, 2019). "In addition, high mobility group box-1 (HMGB1) binds to the sema3A genomic locus and inhibits sema3A expression, resulting in increased migration of tumor cells." (PMID 30696103, 2019). "HMGB1 is also pivotal in the maintenance of chronic inflammation and a “wound healing” type of immune response that ultimately contributes to the onset of carcinogenesis and tumor progression." (PMID 31379812, 2019). "Moreover, previous studies reported that HMGB1 enhances the functions of key immune suppressor cells such as myeloid-derived suppressor cells and regulatory T cells, inhibiting anti-tumor immune responses." (PMID 31399104, 2019). "Thus, effective methods of treatment include combining immunotherapy with targeting PD1+ TAMs and tumor-derived exosomal HMGB1 to resuscitate immune function in individuals suffering from ESCC." (PMID 30796203, 2019). "These different tumor models may explain some of the discrepancies in the literature concerning the prognostic value of HMGB1." (PMID 30744691, 2019). "It is unknown whether HMGB1 mediated DCs expansion could directly contribute as a cellular source for the tumor formation." (PMID 31731454, 2019). "To verify whether HMGB1 is essential for PCa oncogenesis, we first analyzed the endogenous protein expression of HMGB1 in four tumor-derived PCa cell lines (PC-3, DU145, 22Rv1, and LNCaP) by Western blotting." (PMID 31410208, 2019). "HMGB1 can also be actively secreted by different types of cell such as monocytes, macrophages, dendritic cells, natural killer cells, endothelial cells, and tumor cells." (PMID 31731454, 2019). "HMGB1 has also been demonstrated to facilitate the recruitment of neutrophils and natural killer (NK) cells into the tumor microenvironment of a xenograft model of breast cancer in athymic mice, where both populations were required for cyclophosphamide to control tumor growth." (PMID 31379850, 2019). "Indeed, HMGB1 contributes to immune escape and tumor progression in vivo by stimulating the proliferation of MDSCs as well as increasing their T cell-inhibitory properties." (PMID 31379812, 2019). "During tumor progression and treatment, HMGB1 has been shown to play different roles in facilitating both cell survival and death by modulating various signaling pathways, including inflammation, gene transcription, autophagy, metastasis, metabolism, and apoptosis." (PMID 31410208, 2019). "Similarly, a study using mouse models showed that HMGB1-RAGE-signaling blockade suppressed tumor growth in which both RAGE and HMGB1 were expressed." (PMID 31399104, 2019). "We investigated the tumor biological effects of HMGB1 and RAGE interaction." (PMID 31100066, 2019). "Nevertheless however, the precise mechanisms by which actively or passively released extracellular HMGB1 functions on tumor cells’ fate remain unclear." (PMID 30988279, 2019). "In addition, TIM-3 interactions with the high mobility group box 1 (HMGB1) protein, which is involved in the recruitment of nucleic acids into endosomes to be sensed by the innate immunity, impairs this mechanism promoting tumor escape." (PMID 30941125, 2019). "However, less is known about the involvement of extracellular HMGB1 in impairing radiation response and its exact role in modulating the tumor immune microenvironment after XRT." (PMID 31015520, 2019). "Thus, it is considered that HMGB1 promotes anticancer drug resistance by enhancing stemness through the interaction between tumor stromal cells and cancer cells." (PMID 31905926, 2019). "The release of HMGB1 from tumor cells in response to chemotherapy or radiation therapy was found to activate antigen presenting cells such as dendritic cells and to induce their priming of T cells involved in anti-tumor immune response." (PMID 31015520, 2019).